BTLA (B and T lymphocyte associated)
Diseases named in the same sentence as BTLA in open-access papers (continued):
Sharing a sentence is not in itself a finding about the gene and the disease.
tumor (continued). "We hypothesized that HVEM expression on hematopoietic tumor cells may serve as a cell extrinsic factor that can modulate the anti-tumor response by co-inhibiting the function of T cells and NK cells through BTLA." (PMID 37033927, 2023). "B and T lymphocyte attenuator (BTLA) in tumor cells could inhibit the activation of B cells, T cells, and macrophages by binding to TNFRSF14." (PMID 37173968, 2023). "In this context, a soluble form of HVEM (sHVEM) might be effective to restore tumor suppression upon binding to BTLA on cancer cells." (PMID 37649037, 2023). "The alternative immune checkpoints such as PD-1, CTLA-4, T-cell immunoglobulin domain and mucin domain-3 (TIM-3), B- and T-lymphocyte-associated (BTLA), which were detected on cytotoxic CD8+ T cells with a gradual and continuous upregulation, impair the recognition and killing of tumor cells." (PMID 36776832, 2023). "sBTLA could interact with membrane HVEM on tumor cells, thereby blocking BTLA/HVEM axis and promoting tumor growth via the ERK1/2 pathway." (PMID 37256126, 2023). "Moreover, IFNγ production by tumor-specific CD8+ T-cells in response to melanocytic antigens has been shown to be impeded via BTLA signaling." (PMID 36291815, 2022). "Here, we show that BTLA is expressed across a broad range of tumor cells." (PMID 36552785, 2022). "Consistently, our results showed that BTLA expressed by NSCLC cells inhibits tumor growth in vitro." (PMID 36552785, 2022). "There is currently no meta-analysis of the relation between BTLA rs1982809 polymorphism and tumor susceptibility." (PMID 35945755, 2022). "In addition, exhausted CD4+ T cells, characterized by high expression of CXCL13 and BTLA, which are T follicular helper markers, were mainly collected from the tumour tissue." (PMID 35184398, 2022). "To explore whether BTLA is expressed on tumor cells, we analyzed the expression profile of BTLA in The Cancer Genome Atlas (TCGA) and found that BTLA was widely transcribed in 32 cancer tissue types." (PMID 36552785, 2022). "Moreover, the strong correlation between CD79A and risk score, B cells, T cells, TIGIT, BTLA, CD27, and TNFRSF17 revealed the crucial role of CD79A in regulating the tumor microenvironment (TME) in LUAD patients." (PMID 35295857, 2022). "In contrast, overexpression of BTLA or HVEM inhibits tumor cell proliferation and colony formation." (PMID 36552785, 2022). "Together, these data also suggest that BTLA may function across a broad range of tumor types, and tumor cell-intrinsic BTLA plays an antagonist function in different tumor types/cell lines." (PMID 36552785, 2022). "These tumor cells escape from the immune system by the use of BTLA–HVEM pathway since impeding the signaling of BTLA–HVEM in the cell culture of naive mice splenocytes with B16F1 cells ameliorates specific cytotoxicity to B16F1 cells and the synthesis of IL-2 and IFN-γ." (PMID 32902664, 2021). "However, activation of BTLA significantly reduced the cytotoxicity and increased tumor burden in the mouse xenograft model." (PMID 33542232, 2021). "The aim of this work was to elucidate whether BTLA/HVEM axis may induce diminished NK cell-mediated anti-tumor responses." (PMID 33917094, 2021). "Furthermore, BTLA was also expressed in tumor cells of non-small cell lung cancer (NSCLC) patients and the BTLA levels were significantly higher in patients with lymphatic metastasis and high tumor pathological stage." (PMID 34163466, 2021). "BTLA was generally expressed at a low percentage of tumor-infiltrating CD8+ T cells." (PMID 34163466, 2021). "Further, as previously reported, BTLA blockade decreased the production of the immunosuppressive and tumor-promoting cytokine IL-10 by B cells, suggesting that targeting BTLA signaling may restore, at least in part, NK cell immune competence." (PMID 33917094, 2021).
tumor (continued). "This expression of BTLA on innate antigen-presenting cells (APCs) and its ligand, Herpesvirus entry mediator (HVEM), on T cells from reovirus-infected tumors was in keeping with a role for the HVEM-BTLA pathway in promoting the potent anti-tumor memory response observed." (PMID 33665363, 2021). "Moreover, we have shown that tumor-specific CD8+ T cells are inhibited in melanoma patients through HVEM/BTLA signaling." (PMID 34208480, 2021). "Up-regulation of BTLA is involved in the inhibition of anti-tumor immunity in cancer tissues." (PMID 34066839, 2021). "Interestingly, clear trends indicated that risk score positively correlated with tumor microenvironment (TME) scores and immune checkpoints TIGIT, CTLA4, and BTLA." (PMID 34712369, 2021). "B and T lymphocyte attenuators (BTLAs) were reported to be identified mostly on B lymphocytes rather than on T lymphocytes and natural killer cells, and the combination of chemotherapy and the anti-BTLA antibody reduced the peritoneal tumor volume and extended survival in tumor-bearing mice." (PMID 34461858, 2021). "As a result, BTLA is found to play dual roles in tumor and infection immunity, and the function of BTLA in related diseases may be context specific." (PMID 33859648, 2021). "The results indicated that tumor could induce enhanced expression of BTLA by T cells, impair T cell functions, thus led to systemic immunosuppression state." (PMID 34163466, 2021). "Additionally, we found the co-inhibitory checkpoint BTLA to be significantly downregulated on all T cell subsets isolated from the tumor." (PMID 32707816, 2020). "A previous study revealed that BTLA detected in epithelial ovarian carcinoma (EOC) tissues can predict poor outcomes of patients, and BTLA inhibitor combined with chemotherapy could enhance immune activation and produce effective anti-tumor effects." (PMID 33718105, 2020). "Moreover, the BTLA’s role in regulating tumor immune cells was qualified by the correlation between BTLA expression and the immune cells gene markers in CRC." (PMID 32793631, 2020). "Ongoing clinical trials are evaluating the anti-tumor activity of recombinant humanized anti-BTLA mAbs including JS004 in advanced solid tumors (NCT04278859) and recurrent/refractory malignant lymphoma (NCT04477772) and TAB004 in metastatic and unresectable solid tumors (NCT04137900)." (PMID 33167514, 2020). "Accordingly, to preclinically explore whether the combination of chemotherapy and BTLA inhibition has a synergistic impact on generating more potent anti-tumor effects, the mAb 6A6 was used for in vivo BTLA inhibition via variRous treatment protocols." (PMID 31753019, 2019). "Besides, the other two molecules, AKT and STAT3, are not only involved in regulating BTLA expression but also modulating several signaling pathways in the process of tumor progression." (PMID 31753019, 2019). "Consequently, we evaluated the anti-tumor effects of chemotherapy combined with various BTLA-related inhibitors such as anti-BTLA Ab, LY294002, and BP-1-102 (Fig. 3f1)." (PMID 31753019, 2019). "Thus, blocking the BTLA signaling pathway inhibits T-cell function, “awakens” cancer recognition by the immune system, and clears tumor cells." (PMID 30984188, 2019). "Furthermore, mice treated with paclitaxel and anti-BTLA Ab 20 μg/mouse were re-challenged with WF-3/Luc tumor cells 100 days after the first tumor challenge." (PMID 31753019, 2019). "In cancer immunotherapy, combining antibodies to PD-1 and BTLA might thus also be of therapeutic benefit in conditions in which a tumor mass is heterogeneous in term of PD-1 and BTLA ligand expression." (PMID 31189114, 2019). "Therefore, chemotherapy combined with anti-BTLA Ab can generate more potent anti-tumor effects than chemotherapy or anti-BTLA Ab alone." (PMID 31753019, 2019). "Furthermore, inhibition of BTLA combined with chemotherapy can promote immune activation and generate potent anti-tumor effects in an animal model." (PMID 31753019, 2019).
tumor (continued). "However, the anti-tumor effects of paclitaxel combined with various BTLA-related inhibitors were different." (PMID 31753019, 2019). "Work by Derré and colleagues demonstrated that although BTLA is down-regulated during activation and differentiation, this receptor is prominently expressed on human T cells in the tumor microenvironment and can function to inhibit tumor-specific T cells." (PMID 30233564, 2018). "However, recent studies indicate that the role of BTLA in tumor-resident T cells is complex, as engagement by its ligand HVEM inhibits proliferation and cytokine production but promotes survival of tumor-infiltrating lymphocytes (TILs)." (PMID 30233564, 2018). "Given the role of type I NKT cells in anti-tumor immunity, we wondered whether inhibiting BTLA signaling would affect tumor progression in the PyMT model." (PMID 29518903, 2018). "While BTLA may promote T cell survival, it decreases proliferation and activity, thereby promoting peripheral tolerance, but limiting anti-tumor immunity." (PMID 29518903, 2018). "Eventually, these studies might help to gauge the potential of BTLA as a target of tumor immunotherapy and to devise immune checkpoint inhibitors that optimally target this pathway." (PMID 30233564, 2018). "Antibody treatment with anti-CTLA-4 (p<0.02), anti-BTLA (p<0.01), anti- PD-L1 (p<0.01), anti- Lag-3 (p<0.001) and anti- PD-1 antibodies (p<0.02) led to a modest but a significant delay in tumor growth in MC-38 bearing mice (p values compared to mice that received isotype control antibody)." (PMID 27050669, 2016). "Similarly, BTLA blockade combined with active immunization enhanced anti-tumor immunity and can lead to regression of large adenocarcinomas in mice." (PMID 26347741, 2015). "Interestingly, BTLA+ NK cells are often enriched in tumor tissues, suggesting that this pathway may be actively co-opted by tumors to silence innate immunity." (PMID 41471273, 2025). "However, translating these findings into clinical strategies will require a deeper understanding of how BTLA expression on different B cell subsets varies across tumor types and disease stages, as well as the impact of BTLA inhibition on overall immune homeostasis." (PMID 41471273, 2025). "Thus, targeting BTLA in combination with macrophage-modulating strategies may provide synergistic therapeutic potential in reshaping the tumor immune microenvironment." (PMID 41471273, 2025). "Furthermore, BTLA levels were related to tumor-infiltrating (TI) immune cell levels." (PMID 38233898, 2024). "Interestingly, BTLA, CD200, IDO1, LAG3, TNFSF14, etc., were overexpressed in the low-risk group, suggesting that low-risk patients may get better treatment outcomes in tumor immunotherapy." (PMID 38169540, 2024). "Moreover, improved response rates could be displayed for tumor patients when antibodies directed against BTLA were used in combination with anti-PD1/PD-L1 therapies." (PMID 38928307, 2024). "Furthermore, considering the similarity and antitumor effect of tumor cell-intrinsic BTLA function to PD-1, we also speculate that when the BTLA monoclonal antibody is used to treat tumors, there may also be similar adverse effects such as PPD or HPD." (PMID 36552785, 2022). "As BTLA regulates several downstream signaling pathways including PI3K/AKT, NF-κB, and ERK1/2 in T or B cells, and to further examine whether these signaling pathways are regulated by BTLA expressed on tumor cells, we performed the RNA sequencing (RNA-Seq) of BTLA knockdown (KD) cells." (PMID 36552785, 2022). "Moreover, an increase of tumor-specific T cell responses upon BTLA-blockade has been reported." (PMID 36081508, 2022). "Thus, this study clearly revealed that tumor cells contain BTLA and HVEM positive subpopulations." (PMID 36552785, 2022). "Therefore, we hypothesized that BTLA inhibits tumor growth by inactivating the ERK1/2 pathway in cancer cells." (PMID 36552785, 2022).
tumor (continued). "However, since BTLA and HVEM are highly expressed on T cells, whether BTLA blockade may promote T cell-mediate anti-tumor responses in patients with CLL deserves further investigations." (PMID 33917094, 2021). "Overall, we propose a model in which treatment with the anti-HVEM mAb would block the HVEM/BTLA inhibitory signaling on CD8+ TILs that would increase their proliferation and numbers, associated with a reduction of their exhausted phenotype, ultimately leading to better tumor control." (PMID 34208480, 2021). "Therefore, chemotherapy combined with BTLA-related inhibitors or antibody-mediated B cell depletion could generate different but more potent anti-tumor effects than chemotherapy alone." (PMID 31753019, 2019). "We are thus postulating that the high spare respiratory capacity and the high OCR that we observed in TIL grown in high oxygen environment, more specifically the CD8+BTLA+ cells, could therefore result in enhanced survival and persistence after transfer, which could confer better tumor control." (PMID 27057427, 2016). "Finally, the finding that antagonism of negative T-cell regulators, such as cytotoxic T-lymphocyte-associated (CTLA) protein-4 and B- and T-lymphocyte attenuator (BTLA), can augment the antitumor immune response confirms that patients mount an immune-specific response to their tumor." (PMID 22110523, 2011). "Especially, a positive correlation between ACAA1 expression in tumor cells and six immune checkpoint-related genes, namely CD27, PDCD1, CD86, BTLA, TIGIT, and CD28, on immune cells within the tumor microenvironment." (PMID 41277949, 2025). "In the tumor microenvironment, HVEM is often expressed on cancer cells, enabling them to suppress BTLA+ immune cells via direct contact, thereby promoting immune evasion and correlating with adverse clinical outcomes." (PMID 41471273, 2025). "A unique feature of BTLA-mediated immune evasion lies in its interaction with HVEM, which is frequently expressed on tumor cells themselves." (PMID 41471273, 2025). "Potential candidates under investigation include BTLA expression levels on TILs, HVEM expression on tumor or stromal cells, and transcriptional signatures reflecting T cell exhaustion phenotypes." (PMID 41471273, 2025). "The therapeutic potential of anti-BTLA immunotherapy, as well as the corresponding changes of TME, in the FXRhiPD-L1lo NSCLC subtype were assessed using a syngeneic mouse tumor model." (PMID 40985894, 2025). "Our in vivo treatment experiments show that targeting HVEM/BTLA pathway with anti-BTLA significantly decreased tumor growth and prolonged OS in FXRhiPD-L1lo LLC tumor–bearing mice, in comparison with those bearing mock LLC tumors." (PMID 40985894, 2025). "HVEM and its inhibitory receptors BTLA and CD160 have become the focus of intensive tumor research as a potential new therapeutic target or prognostic marker." (PMID 40243455, 2025). "The ligand of BTLA is Herpes Virus Entry Mediator (HVEM, or TNFRSF14, is a TNF‐receptor family member), which is up‐regulated in various tumours." (PMID 40415479, 2025). "The collective effect of BTLA expression across these innate and myeloid compartments is the reinforcement of an immunosuppressive TME that impairs both direct tumor cell killing and the priming of effective adaptive responses." (PMID 41471273, 2025). "The findings demonstrated that cluster 1 has highly expressed immunosuppressive sites such as BTLA, CD200, CD200R1, CD44, HAVCR2, etc. that promote immunosuppression and tumor formation." (PMID 38347320, 2024). "Functional studies showed that BTLA blockade increased the percentage of IFNγ + NK-cells and IFNγ + CD8 + T-cells, decreased the secretion of IL-10 by CLL B-cells, and increased tumor cell lysis." (PMID 38233898, 2024). "Immunosuppressive molecules, such as PD‐L1, CTLA‐4, TIM‐3, BTLA, CD160, LAG3, and 2B4,73 not only dampen the tumor's immune response but also impact the efficacy of OVs in infecting tumor cells." (PMID 39399642, 2024).
tumor (continued). "Various studies have suggested that the markers of T‐cell exhaustion, such as CTLA‐4, BTLA, LAG‐3, 2B4, TIM‐3, CD160, and PD‐1, induce the functionally impaired state and thereby suppress the proliferation of the exhausted T cells in tumor tissues." (PMID 38204220, 2024). "According to this study, PTK6 expression was positively correlated with CD160, IL10RB, and PVRL2 while being negatively correlated with ADORA2A, BTLA, CSF1R, and KDR in the other tumor types." (PMID 38573548, 2024). "Follicular helper T lymphocytes by decreasing BTLA surface expression, promoted the upregulation of the anti-apoptotic protein BCL-2 (via CD40L) in B germinal centers, favoring tumor growth." (PMID 37649037, 2023). "As reviewed herein, recent accumulative evidence is shedding light on the key role of BTLA and HVEM in tumor immune escape." (PMID 37649037, 2023). "As LAG-3, TIM3, BTLA, and TIGIT belong to the co-inhibitory receptors, which are known to impair anti-tumor immunity." (PMID 37946136, 2023). "Consistently, the features for suppression of anti-tumor immunity were dominantly elevated in the CDC20-high group, such as BTLA, CTLA4, CD4, ITGAM, C4B, CD163, and CD206." (PMID 37528490, 2023). "CLL not only exhibits exacerbated BTLA levels, HVEM expression is also deeply dysregulated in this tumor." (PMID 37649037, 2023). "Mechanistically, the coordination of BTLA and HVEM inhibits its major downstream extracellular regulated protein kinase (ERK1/2) signaling pathway, thus preventing tumor cell growth." (PMID 36552785, 2022). "Certain positive regulatory factors, such as CD27, CD28, CD30, ICOS, and negative regulatory factors, such as CTLA4, PD-1, BTLA, TIM3, andLAG3, at immune checkpoints affect the recognition and apoptotic ability of the immune system against tumour cells." (PMID 36118669, 2022). "Collectively, these data demonstrate that the BTLA/HVEM axis coordinates to regulate the cell proliferation and signaling pathway in tumor cells." (PMID 36552785, 2022). "The immune checkpoint TNFSF14 in Neutrophils, NK Cells, and Monocytes and BTLA in Treg Cells, Granulosa Cells, and B Cells interact with LTBR and TNFRSF14 in Cancer Cells to mediate cytotoxicity and promote tumor killing." (PMID 36401283, 2022). "Simultaneous up-regulation of iICPs (for example, BTLA) and corresponding ligands at the CAFs (for example, HVEM) leads to inhibition of CTLs in the tumor medium, which eventually leads to more inhibition of immune cells in the TME." (PMID 36275750, 2022). "BTLA expression on CD4+ T cells and CD8+ T cells in the tumor microenvironment of EOC was also studied, which was 37.6% and 15.7%, respectively." (PMID 35204342, 2022). "BTLA, as a member of the CD28 superfamily, was found to be expressed in tumor-infiltrating lymphocytes." (PMID 36467089, 2022). "BTLA and CD70 concentrations were found to be higher in cancers with tumor cells present in the peritoneal fluid (p = 0.04, p = 0.02, respectively)." (PMID 35204342, 2022). "We noted that high BLCA tumor expression of TNFRSF14 or CD160 trended toward improved prognosis compared with either TNFSF14, LTA, or BTLA." (PMID 34858395, 2021). "To examine if tumor-infiltrating MAIT cells have an exhausted phenotype, we analyzed their expression of the surface markers PD-1, Tim-3, CD39, TIGIT, BTLA, and LAG3, which have all been used to identify exhausted conventional CD8+ T cells in tumors." (PMID 33885944, 2021). "The opposite was observed in the tumor microenvironment following treatment, with an increase in HVEM and a reduction of BTLA gene and protein expression, with a concomitant increase in LTA and LIGHT, two other ligands for HVEM." (PMID 34208480, 2021). "With increased tumor PD-L1, the expression of inhibitory checkpoint molecules (ICMs), including ADORA2A, BTLA, CD160, and PDCD1, was downregulated while the expression of IDO1 was upregulated." (PMID 33754038, 2021).